SDC4 (syndecan 4)
Diseases named in the same sentence as SDC4 in open-access papers (continued):
Sharing a sentence is not in itself a finding about the gene and the disease.
Obesity (8 papers, 2018 to 2025). Accumulation of substantial excess body fat. "The objective of the study was to evaluate the effects of Sdc4 deficiency on body composition and energy balance components as well as cardiovascular disease-associated metabolic parameters in diet-induced obesity." (PMID 31752080, 2019). "Here, we elicited obesity in homozygous male and female Sdc4-deficient (Sdc4-/-) mice and their age-matched WT mice by using a standard HFD treatment protocol." (PMID 31752080, 2019). "However, the specific function and underlying mechanism of adipocyte-derived Sdc4 in obesity remain elusive." (PMID 40180176, 2025). "•Sdc4 deficiency enhances adaptive thermogenesis and alleviates obesity." (PMID 40180176, 2025). "Here, we investigated whether deletion of Sdc4 promotes metabolic derangements associated with diet-induced obesity by feeding homozygous male and female Sdc4-deficient (Sdc4-/-) mice and their age-matched wild-type (WT) mice a high-fat diet (HFD)." (PMID 31752080, 2019). "Thus, our results suggest that Sdc4 deficiency decreases food intake in HFD-induced obesity." (PMID 31752080, 2019). "Here, the use of adipocyte-Sdc4-KO mice in the present study provides a clear picture of the regulatory role of adipocyte-derived Sdc4 in obesity." (PMID 40180176, 2025). "In conclusion, evidence from genetic ablation and exogenous treatment in in vitro models ofadipocytes demonstrate, for the first time, that shed Sdc4 from adipocytes during obesity acts as a novel suppressor of lipolysis through the FGF2/FGFR1 axis." (PMID 40180176, 2025). "Given the fact that deletion of Sdc4 in adipocytes abolishes Sdc4 shedding thus attenuating diet-induced body fat gain and other metabolic syndrome, targeting shed Sdc4 is a potential therapeutic strategy for obesity." (PMID 40180176, 2025). "Overall, our study reveals that adipocyte-derived shed Sdc4 is a novel suppressor of lipolysis, contributing to decreased energy expenditure, thus exaggerating obesity." (PMID 40180176, 2025). "By constructing a ceRNA regulatory network, we have identified novel lncRNA-miRNA-mRNA interactions, highlighting MEG3, hsa-miR-7974, and SDC4 as central nodes in the molecular circuitry of obesity." (PMID 41199597, 2025). "In the present study, the roles of adipocyte-specific Sdc4 and its underlying mechanism in regulating lipolysis in the development of obesity were investigated using adipocyte-specific Sdc4 knockout mice (AT-Sdc4 KO) and wild-type (WT) littermates." (PMID 40180176, 2025). "Another recent study showed that Sdc4 expression is increased in adipose tissue of obese mice, and Sdc4 protein shedding can inhibit lipolysis, leading to obesity." (PMID 41199597, 2025). "The identification of a ceRNA network, where MEG3, AC020916.1, AC008738.7, XLOC_003001, and LOC112268144 act as molecular sponges for hsa-miR-7974 to regulate SDC4 expression, suggests potential new insights into the pathogenesis of obesity." (PMID 41199597, 2025). "Given that adipogenesis contributes to fat mass gain during diet-induced obesity, whether Sdc4 is involved in adipocyte differentiation was explored." (PMID 40180176, 2025). "•Diet-induced obesity triggers syndecan 4 (Sdc4) shedding from adipocytes." (PMID 40180176, 2025). "Hence, these findings highlight the therapeutic potential of targeting shed Sdc4 to alleviate obesity through improving lipid metabolism." (PMID 40180176, 2025). "Targeting shed Sdc4 is a potential therapeutic strategy for obesity." (PMID 40180176, 2025). "Obesity predisposes to hepatic steatosis, a condition characterized by the deposition of lipid droplets in the liver; therefore, we next measured hepatic TG in HFD-fed female Sdc4-/- and WT mice." (PMID 31752080, 2019).
Obesity (continued). "Genetic ablation of Sdc4, specifically in adipocytes, promotes whole-body energy expenditure in mice, associated with enhanced lipolytic capacity and WAT browning, which lowers chronic inflammation and alleviates diet-induced obesity and its related metabolic syndrome." (PMID 40180176, 2025). "However, under pathological conditions such as obesity, chronic elevation of shed Sdc4 leads to the exaggerated inhibition of lipolysis not only impairs thermogenesis but also induces adipose tissue hypertrophy and eventually leads to insulin resistance and metabolic diseases." (PMID 40180176, 2025). "Moreover, SDC4 upregulation could be a consequence of obesity-related inflammation or adipocyte hypertrophy." (PMID 41199597, 2025). "Therefore, circulating shed Sdc4 may serve as a potential biomarker of obesity and its related complications." (PMID 40180176, 2025). "Adipocyte-specific deletion of Sdc4 promotes lipolysis and WAT browning, thereby raising whole-body energy expenditure to protect against diet-induced obesity." (PMID 40180176, 2025). "In this study, we identified that adipocyte-derived shed Sdc4 is a novel suppressor of lipolysis leading to attenuated FFA-oxidation, reduced adaptive thermogenesis, and exaggerated adipose tissue dysfunction, thus aggravating obesity." (PMID 40180176, 2025). "We also found increased Sdc4 transcript levels in the LFABP−/− iWAT, compared to the WT, further corroborating that ECM remodeling may influence adipose tissue remodeling during obesity development." (PMID 40497936, 2025). "Subsequently, the shed-Sdc4-induced FGF2/FGFR1 activation inhibits adipocyte lipolysis by suppressing HSL phosphorylation, which uncovered a specific mechanism of shed Sdc4 in the development of obesity." (PMID 40180176, 2025).
colon carcinoma (7 papers, 2008 to 2026). "In normal epithelial cells and tissues, the expression level of syndecan-4 is high, however, syndecan-4 is significantly reduced in highly metastatic colon carcinoma cells (KM1214)." (PMID 33810567, 2021). "SDC4 expression is downregulated in colon carcinoma cells and it is upregulated in normal breast tissue compared to malignant breast tissue." (PMID 34282767, 2021). "In turn, experimental lung metastasis of the murine colon cancer cell line MC-38 resulted in an induction of syndecan-4 expression in blood vessels at the metastatic site, suggesting a possible role for this proteoglycan in the metastatic niche." (PMID 33810567, 2021). "Hypoxia is one of the factors regulating syndecan-4 expression in human colon cancer cells, as it can induce its expression, along with alpha 5 integrin." (PMID 33810567, 2021). "Moreover, the recombinant syndecan-4 ectodomain is capable of inducing the expression of the epidermal growth factors erb-b2 and erb-b3 in colon cancer cells, suggesting a regulatory crosstalk between these receptor tyrosine kinases and the proteoglycan." (PMID 33810567, 2021). "Interestingly, when both syndecans were coexpressed in colon cancer cells, the syndecan-2 mediated promigratory and adhesive effect was decreased by syndecan-4 and vice versa." (PMID 26378057, 2015). "Interestingly, hetero-oligomerization with syndecan-2 reduces both syndecan-4-dependent PKCα activation and cell adhesion and syndecan-2-mediated migration and anchorage-independent growth in colon cancer cells, suggesting a functional interplay of syndecans in tumor progression." (PMID 33810567, 2021). "Syndesmos (SDOS), which regulates cytoskeletal organization via interaction with syndecan-4 in fibroblasts, was under-expressed in highly metastatic HCT116 colon cancer cells compared to weakly metastatic HT29 cells." (PMID 42156364, 2026).
glioblastoma (7 papers, 2016 to 2023). The most malignant astrocytic tumor (WHO grade IV). "SDC4 has been associated with the outcome of a WT1 immuno therapy in glioblastomas." (PMID 32604718, 2020). "In this study, we identified SDC-4 as a biomarker to predict clinical outcome using peripheral blood mononuclear cells obtained from patients with glioblastoma, a malignant brain tumor, who were treated with WT1 peptide vaccine." (PMID 28116121, 2016). "Interestingly, syndecan-4 mRNA expression has been indicated as a novel marker for the prediction of glioblastoma multiforme patients’ response to treatment with the WT1 peptide vaccine, and its expression is altered in pediatric astrocytoma." (PMID 33810567, 2021). "The SDC4-α5β1 integrin mediated cell adhesion to fibronectin reduces tumor cell proliferation, whilst the tenascin-C-mediated inhibition of SDC4-fibronectin interaction and consequently the impaired fibronectin-induced signaling enhances the proliferation of glioblastoma cells." (PMID 34282767, 2021). "In vitro analysis of glioblastoma as an acutely angiogenic tumor type revealed that glioblastoma-derived exosomes contain high levels of miR-221, proteoglycans glypican-1 and syndecan-4 that increase revascularization via enhancing proliferation and formation of endothelial cells and tubules." (PMID 30940145, 2019). "In addition, many partners, such as solute carrier family 34 member 2 (SLC34A2), cluster of differentiation 74 (CD74), fused in glioblastoma, Syndecan 4 (SDC4) and Ezrin (EZR), are rearranged with ROS1 in NSCLC." (PMID 35628598, 2022). "Ochieng and collaborators have demonstrated that knockdown of syndecan-4 significantly attenuated the invasive capacity and uptake of labeled exosomes and FNH (fetuin-A and histones) nanoparticles of LN229, a highly aggressive glioblastoma cell line." (PMID 33810567, 2021).
glioma (7 papers, 2008 to 2023). A benign or malignant brain and spinal cord tumor that arises from glial cells (astrocytes, oligodendrocytes, ependymal cells). "Nuclear glypican (Gpc) has been found in neurons and glioma cells, syndecan-4 (Sdc-4) in cardiomyocytes, Sdc-1 in fibrosarcoma cells, and Sdc-2 in the nucleus of tumour cells in osteochondromas." (PMID 33922532, 2021). "Syndecan-4 is highly expressed on the surface of glioma cells." (PMID 33810567, 2021). "Syndecan-4 appears regularly spread in the plasma membrane of U87 glioma cells (Scr)." (PMID 18545691, 2008). "TNC is a component of the glioma ECM that binds to integrin receptors, EGF receptor (EGFR), and SYNDECAN 4 (SDC4) and regulates angiogenesis, proliferation, and cell migration." (PMID 36707509, 2023). "MES-like glioma cells expressed multiple receptors for ANGPTL4, including syndecans SDC2, SDC3, and SDC4 as well as WNT5A receptor FZD6, suggesting that these pathways may be responsible for the enrichment of GSCs in ECMhi tumors." (PMID 37292803, 2023). "MES-like glioma cells expressed multiple receptors for ANGPTL4, including SDC2 SDC3, SDC4, and integrins ITGA5 and ITGB1, suggesting that the ANGPTL pathway may be responsible for the enrichment of GSCs in ECMhi tumors." (PMID 37884531, 2023).
Hypertension (7 papers, 2014 to 2024). The presence of chronic increased pressure in the systemic arterial system. "We and others previously reported that variation in the SDC4 gene was associated with several components of the metabolic syndrome, including intra-abdominal fat, fasting glucose and triglyceride levels, and hypertension, in human cohorts." (PMID 37461091, 2023). "We report that syndecan-4 gene SNP rs1981429 variant TT was significantly associated with hypertension, as compared to variants TG and GG at the age of 50 years." (PMID 25410619, 2014). "The mechanisms behind associations of syndecan-4 polymorphisms with essential hypertension, BMI, and CAD need further studies." (PMID 25410619, 2014). "In conclusion, syndecan-4 polymorphisms were associated with essential hypertension, BMI, and CAD prevalence in the TAMRISK study." (PMID 25410619, 2014). "Syndecan-4 polymorphisms were associated with essential hypertension, BMI, and CAD prevalence in the TAMRISK study." (PMID 25410619, 2014). "Growing evidence suggests that elevated levels of both shed SDC1 and SDC4 are associated with hypertension and cardiovascular diseases, but their relationships with cardiovascular risk factors in healthy individuals are unknown." (PMID 33668381, 2021). "The relationship between syndecan-4 and mechanical stress may explain the increase in soluble plasma syndecan-4 observed in patients with treatment-resistant hypertension compared with healthy controls." (PMID 38912739, 2024).
papillary thyroid cancer (7 papers, 2020 to 2025). "SDC4 gene silencing attenuates the epithelial-mesenchymal transition and promotes apoptosis of papillary thyroid cancer cells." (PMID 33962639, 2021). "Silencing of SDC4 expression decreases migration and invasion of papillary thyroid cancer cells and inhibits epithelial-mesenchymal transition via Wnt/beta-catenin pathway." (PMID 34282767, 2021). "Using a microarray, two recent studies have shown that syndecan-4 expression levels among the papillary thyroid cancer tissues are higher than that in normal thyroid tissues." (PMID 33810567, 2021). "In a cancer context, silencing of syndecan-4 expression was shown to exhibit an antitumoral effect on human papillary thyroid carcinoma cells by affecting apoptosis and epithelial-to-mesenchymal transition via the Wnt/beta-catenin pathway." (PMID 33810567, 2021). "In addition, knockdown of syndecan-4 in human papillary thyroid carcinoma cells promoted apoptosis via the Wnt/beta catenin pathway." (PMID 33810567, 2021). "Moreover, SDC4 silencing is shown to repress EMT in papillary thyroid cancer cells." (PMID 34282767, 2021). "Besides, overexpression of SDC4 promoted EMT and inhibited cancer cell apoptosis by activating the Wnt/β-catenin signaling pathway in human papillary thyroid cancer." (PMID 39107908, 2024). "Interestingly, syndecan-4 gene silencing represses EMT, and enhances cell apoptosis by suppressing the activation of the Wnt/β-catenin signaling pathway in human papillary thyroid carcinoma." (PMID 33810567, 2021).
pneumonia (7 papers, 2016 to 2025). An acute, acute and chronic, or chronic inflammation focally or diffusely affecting the lung parenchyma, caused by an infection in one or both of the lungs (by bacteria, viruses, fungi, or mycoplasma.). "Based on the expression pattern of syndecans in the cornea, we next carried out experiments to determine if Sdc1 and Sdc4 modulate the pathogenesis of S. pneumoniae corneal infection." (PMID 33293379, 2020). "Addition of both suPAR and syndecan-4 to the Pneumonia Severity Index significantly improved their prognostic accuracy, with an AUC of 0.885." (PMID 29368632, 2018). "Studies have demonstrated that levels of syndecan-4 increase in response to bacterial inflammation, and that syndecan-4 possesses an anti-inflammatory function in acute pneumonia." (PMID 29368632, 2018). "We also found higher serum syndecan-4 levels in hospitalized patients with bacterial pneumonia than in healthy subjects, and the syndecan-4 levels tended to increase over the course of pneumonia in those patients with a favorable prognosis." (PMID 28467516, 2017). "The prominent phenotype of Sdc1−/− corneas also indicated that Sdc4 and other HSPGs do not functionally compensate for the loss of Sdc1 in S. pneumoniae corneal infection." (PMID 33293379, 2020). "This study also found that serum syndecan-4 levels are higher in hospitalized bacterial pneumonia patients than in healthy individuals, and that syndecan-4 levels tend to increase over the course of pneumonia in patients with favorable prognosis." (PMID 31600983, 2019). "Among the top consistently chosen variables (that were not DEGs) in our machine learning analysis, Syndecan-4 (SDC4) has been found to be a potential biomarker with an anti-inflammatory function in patients with acute pneumonia." (PMID 33692779, 2021).
pulmonary fibrosis (7 papers, 2017 to 2025). Chronic progressive interstitial lung disorder characterized by the replacement of the lung tissue by connective tissue, leading to progressive dyspnea, respiratory failure, or right heart failure. "The mRNA expression of collagen and α-smooth muscle action (α-SMA) in lung tissues, as well as the histopathological lung fibrosis score and collagen content in lung tissues, were significantly higher in the syndecan-4-deficient mice." (PMID 31600983, 2019). "Recombinant Cxcl10 protein administration inhibits bleomycin-induced pulmonary fibrosis in mice, but this effect is abrogated in Sdc4-/- mice." (PMID 39768150, 2024). "Interaction between syndecan-4 and Cxcl10 in the lung interstitial compartment inhibits fibroblast recruitment and pulmonary fibrosis in mice." (PMID 39768150, 2024). "While there is limited evidence on the role of SDC4 in cancer, it has been shown that interaction between CXCL10 and SDC4 inhibits fibroblast recruitment in pulmonary fibrosis." (PMID 34430923, 2021). "Taken together, this study concludes that syndecan-4 inhibits the development of pulmonary fibrosis, at least in part, through attenuating TGF-β signaling in the lungs." (PMID 31600983, 2019). "For further evaluation of the role of syndecan-4 on pulmonary fibrosis, the effect of syndecan-4 knock-down on TGF-β-induced collagen and α-SMA upregulation in lung fibroblasts was analyzed." (PMID 31600983, 2019). "Lung fibroblasts were analyzed because the cells played a critical role in pulmonary fibrosis and the increase in syndecan-4 had already been demonstrated in the cells from BLM-instilled lung tissues." (PMID 31600983, 2019). "There is limited evidence on the role of syndecan-4 in pulmonary fibrosis." (PMID 31600983, 2019). "The purpose of this study was to identify the role of syndecan-4 in pulmonary fibrosis." (PMID 31600983, 2019). "However, the possibility that other types of cells are involved in the pathogenesis of pulmonary fibrosis cannot be excluded, because syndecan-4 exists in a variety of cells." (PMID 31600983, 2019). "Another effect of syndecan-4 may involve its interaction with the C-X-C motif chemokine ligand 10 (CXCL10), which shows an anti-fibrotic effect upon binding to syndecan-4 in a bleomycin-induced mouse model of pulmonary fibrosis." (PMID 28467516, 2017). "We have previously reported that intratracheal instillation of LPS and viable bacteria into mice increases mRNA expression of syndecan-4 in the lungs, and immunohistochemical analysis showed increased expression of proteoglycans in patients with pulmonary fibrosis including IPF." (PMID 28467516, 2017). "However, the role of syndecan-4 in pulmonary fibrosis remains to be clarified." (PMID 31600983, 2019). "Moreover, more shedding of membrane syndecan-4 must be induced in fibrotic lungs, because MMP levels are reported to be increased in pulmonary fibrosis." (PMID 28467516, 2017).
colorectal cancer (6 papers, 2021 to 2024). A primary or metastatic malignant neoplasm that affects the colon or rectum. "SDC4 expression is significantly correlated with the pathological characteristics that indicate disease progression and inversely associated with disease-free and overall survival, meaning SDC4 emerges as a molecular marker of colorectal cancer cell aggressiveness." (PMID 36358747, 2022). "Consistently, SDC4 overexpression in the invading tumor cells is clearly related to the progression of pathogenesis and is inversely related to the overall survival of patients with colorectal cancer." (PMID 36199068, 2022). "SDC4 levels are increased at the invasion front of colorectal cancer cells." (PMID 36358747, 2022). "In contrast, in neuroblastoma and colorectal cancer, syndecan-4 is downregulated." (PMID 33810567, 2021). "Syndecan-4 (SDC4) is connected to a poor prognosis and the invasion of colorectal cancer cells." (PMID 37228620, 2023).